LDHB (lactate dehydrogenase B)
Description:
Interconverts simultaneously and stereospecifically pyruvate and lactate with concomitant interconversion of NADH and NAD(+).
Synonyms: LDH-B; LDH-H; HEL-S-281; LDHBD; TRG-5
Tractability: Small molecule: a structure with a bound ligand is known; a high-quality ligand is known; it has a high-quality binding pocket; it belongs to a druggable protein family. Antibody: UniProt places it where antibodies can reach, with high confidence. PROTAC: ubiquitination databases record sites on it; its protein half-life has been measured; a small molecule that binds it is known.
Target class: Enzyme; Oxidoreductase
Gene: Protein-coding gene on chromosome 12 (21,635,340 to 21,757,890, reverse strand). Ensembl gene ENSG00000111716.
Subcellular location: Cytoplasm; Mitochondrion inner membrane
Subcellular location (Human Protein Atlas): Cytosol; Primary cilium
Pathways (Reactome):
Metabolism: Pyruvate metabolism
Gene Ontology:
Molecular function: identical protein binding; L-lactate dehydrogenase (NAD+) activity; protein binding; catalytic activity; kinase binding; lactate dehydrogenase activity; NAD binding; oxidoreductase activity; oxidoreductase activity, acting on the CH-OH group of donors, NAD or NADP as acceptor
Biological process: lactate metabolic process; pyruvate catabolic process; NAD+ metabolic process
Cellular component: cytosol; extracellular exosome; membrane; membrane raft; mitochondrial inner membrane; oxidoreductase complex; cytoplasm; mitochondrion
Genetic constraint (gnomAD): Loss-of-function variants: 13 observed, 22.29 expected, observed/expected ratio (o/e) 0.58, 90% interval 0.38 to 0.93. The upper end of that interval is the gene's LOEUF score, 0.93, which puts it in group 3 of 6, group 1 being the genes least tolerant of losing a copy. Missense variants: 295 observed, 345.23 expected, observed/expected ratio (o/e) 0.85, 90% interval 0.78 to 0.94. Synonymous variants: 102 observed, 119.54 expected, observed/expected ratio (o/e) 0.85, 90% interval 0.73 to 1.01.
Homologues: Orthologues: chimpanzee LDHB (100% identical), macaque LDHB (100% identical), mouse Ldhb (98% identical), rat Ldhb (98% identical), guinea pig LDHB (98% identical), pig LDHB (97% identical), tropical clawed frog ldhb (84% identical), zebrafish ldhba (80% identical), zebrafish ldhbb (79% identical). Paralogues in human: LDHA (75% identical), LDHC (69% identical), LDHAL6B (66% identical), LDHAL6A (65% identical), MDH2 (24% identical).
Diseases named in the same sentence as LDHB in open-access papers:
LDHB is named in the same sentence as 122 diseases in open-access papers, as found by Europe PMC text mining. Sharing a sentence is not in itself a finding about the gene and the disease. The quoted sentences say what the papers report.
breast carcinoma (57 papers, 2013 to 2025). "The loss of LDHB inhibits tumor cell proliferation in vitro and tumor growth in vivo, and breast cancer patients with higher expression of LDHB tend to have poorer clinical outcomes." (PMID 38680483, 2024). "Not only GPI but also these glycolysis enzymes, except for LDHB, have been associated with patient’s poor prognosis in breast cancer and colorectal cancer." (PMID 38419074, 2024). "In another study, LDHB was found to be linked to breast cancer by controlling early tumor progression." (PMID 37007972, 2023). "In breast cancers, the expression of the LDHB gene (encodes LDH-1) has been used to evaluate response to neoadjuvant chemotherapy." (PMID 34822416, 2021). "On the other hand, loss of LDHB expression in breast cancer (adenocarcinoma) tissues and cell lines due to promoter hypermethylation has been linked to metastatic development." (PMID 34822416, 2021). "Invasive front of the tumor showed cell-specific protein localization of LDHA in breast cancer cells and LDHB in cancer-associated adipocytes." (PMID 33353120, 2020). "High LDHB expression in basal-like breast cancer has been associated with better pathological complete response rates to neoadjuvant chemotherapy." (PMID 33324565, 2020). "Gene LDHB encodes for the lactate dehydrogenase B protein that was highly expressed in Basal subtype and reported to be a metabolic marker of response to neoadjuvant chemotherapy in breast cancer." (PMID 27634900, 2016). "Conversely, high post-treatment LDHB levels in patients who fail to achieve pCR are indicative of increased proliferative potential and heightened relapse risk, suggesting its potential utility as a predictive marker in breast cancer therapy." (PMID 40733189, 2025). "For instance, LDHB promoter methylation is associated with breast cancer progression." (PMID 37122693, 2023). "To this end, we examined lactate concentration, LDH activity, and isozyme profile, as well as protein expression and tissue localization of LDHA and LDHB in paired biopsies of malignant tumor tissue and tumor-associated adipose tissue from normal-weight and overweight/obese women with breast cancer." (PMID 33353120, 2020). "Herein, we showed that lactate treatment in ER + ve breast cancer cells reduced nectin-4 expression and LDHB KO in ER- cells enhanced its expression." (PMID 40507273, 2025). "Clinically, LDHB expression in breast cancer has emerged as a robust metabolic biomarker predictive of therapeutic response and prognosis." (PMID 40733189, 2025). "We also observed reduced expression of MMP-2 in response to LDHB KO or LDH inhibition in ER- breast cancer cells." (PMID 40507273, 2025). "Herein, we demonstrated reduced expression of IL-6 and IL-8 in response to LDHB KO or LDH inhibition in ER- breast cancer cells." (PMID 40507273, 2025). "LDHB overexpression has been identified as an unfavorable prognostic marker in lung, liver and breast cancers." (PMID 39213172, 2024). "Metabolic proteins including aldehyde dehydrogenase 1 family member A3, L-lactate dehydrogenase B chain, cytochrome b5 type B and elongation factor Tu, and elongation factor 1δ were overexpressed in the breast cancer cells and prostate cancer cells." (PMID 38249992, 2024). "In line with our results, previous proteomic analysis of Adriamycin resistance in breast cancer also suggested a role for LDHB in drug resistance." (PMID 37397367, 2023). "Breast cancer cells expressing high levels of LDHB show basal-like and glycolytic phenotypes, whereas the suppression of its expression reduces their glycolytic dependence." (PMID 37397367, 2023). "The expression of LDHB is significantly increased in response to chemotherapy, suggesting a marker role for this gene in response to neoadjuvant chemotherapy in breast cancer." (PMID 37397367, 2023).
breast carcinoma (continued). "For instance, panepoxydone exerted protective mechanisms against breast cancer initiation and progression by suppressing lactate dehydrogenase A expression levels and reinducing lactate dehydrogenase B expression levels." (PMID 36771106, 2023). "The histone deacetylase inhibitor trichostatin A has been shown to upregulate LDHB expression in breast cancer cells." (PMID 37547725, 2023). "Methylation of the LDHB promoter is often present in breast cancer cells and plays an important role in cancer development and progression." (PMID 36551514, 2022). "HMGB2 promotes the progression of breast cancer by targeting lactate dehydrogenase B and febrile convulsions 1 proteins." (PMID 35962344, 2022). "As a control, MCF7 breast cancer cells, characterized by very low LDHB protein expression levels, exhibited marginal LDHB activity." (PMID 35877003, 2022). "Some studies reveal that there is a link between the presence of LDHB and the enhanced proliferation of lung adenocarcinoma and breast cancer." (PMID 36551514, 2022). "In breast cancer, the expression of LDHB is lower in malignant tumors than the benign tumors and is preferential in cancer-associated adipocytes, implying the tissue specificity of LDHB expression in the tumor cells and stromal cells of TME." (PMID 36612084, 2022). "It has been proposed that pancreatic cancer and breast cancer patients with lower LDHB expression are more likely to show positive responses to treatment, and LDHB has frequently been proposed as a diagnostic and prognostic marker in prostate cancer." (PMID 34680521, 2021). "Our study adds to the molecular mechanism how breast tumor cells alter TAMs metabolism for trophic needs and homeostasis by downregulating LDHB in mouse and human breast cancer tissue." (PMID 34158867, 2021). "This disparity of glucose utilization by different breast cancer types and the differential expression of LDHB makes it an attractive target for anti-tumor treatment." (PMID 34158867, 2021). "In the present study, we have utilized these cell lines and shown that the acquired ER −ve cells as well as normal MCF10A express both LDHA and LDHB whereas expression of LDHB is lost in ER +ve breast cancer cells." (PMID 34744727, 2021). "Immunohistochemistry confirmed that LDHA was primarily localized in breast cancer cells in contrast to LDHB, which was primarily localized in breast epithelial cells within benign breast tumors." (PMID 33353120, 2020). "The abundance of LDHB is abnormally increased in multiple types of cancer, including medulloblastoma, cholangiocarcinoma, oesophageal squamous cell carcinoma and breast cancer." (PMID 32391634, 2020). "LDHB is highly expressed in multiple types of cancer, including medulloblastoma, cholangiocarcinoma, oesophageal squamous cell carcinoma and breast cancer." (PMID 30443978, 2019). "Breast cancer cell lines with glycolytic and basal-like phenotypes expressed high LDHB levels and stable knockdown of LDHB reduced glycolytic dependence." (PMID 31146503, 2019). "In breast cancers, LDHB expression was found to be a marker for neoadjuvant chemotherapy response evaluation." (PMID 31146503, 2019). "HMGB2 expression plays important roles in breast cancer progression by regulating proliferation and the Warburg effect by transcriptional regulation of LDHB and FBP1 activity." (PMID 29463261, 2018). "Otherwise, LDHB has been reported to be an oncogenic protein in multiple tumor types, including uterine cancer, ovarian cancer, colon cancer and breast cancer." (PMID 30419950, 2018). "In particular, the expression of LDHB regulates the glycolytic flux by converting pyruvate to lactate, and indeed, increased LDHB expression has been observed in breast cancer." (PMID 27070597, 2016). "Consistent with selective inhibition of LDHA, the most sensitive breast cancer cell lines to lactate inhibition in hypoxic conditions were cells with low expression of LDHB." (PMID 24280423, 2013).
breast carcinoma (continued). "In addition, LDHB KO or treatment with LDH inhibitors in ER- breast cancer cells reduced their motile ability in part through reducing the expression of IL-6, IL-8, and MMP-2." (PMID 40507273, 2025). "This expression profile was reversed in ER- breast cancer cells upon silencing of the LDHB gene." (PMID 40507273, 2025). "LDHB expression correlates with response to neoadjuvant chemotherapy in breast cancer." (PMID 40790017, 2025). "For example, miR-375 has been shown to downregulate LDHB expression in breast cancer cells." (PMID 37547725, 2023). "It seems that LDHB could be involved in breast cancer resistance to chemotherapy and as a potential marker for tamoxifen resistance." (PMID 36551514, 2022). "Consistent with this, LDHB expression is highly elevated in lung cancer and breast cancer." (PMID 34680521, 2021). "However, LDHB was found to be overexpressed in triple-negative breast cancer cell lines and was correlated with poor prognosis among breast cancer patients; it was also found to be overexpressed in highly glycolytic, mesenchymal breast cancer cell lines." (PMID 34069745, 2021). "LDHB catalyzes the interconversion between pyruvate and lactate and determines the chemotherapy response and prognosis in oral squamous cell carcinoma and breast cancer patients." (PMID 33170151, 2020). "The enzyme LDHB, which was found to be upregulated in the LB- subtype, may help identify breast cancers most likely to respond to neoadjuvant chemotherapy as well as those with the highest risk of relapse that may benefit from additional adjuvant therapy." (PMID 33182810, 2020). "Indeed, LDHA was predominantly localized in breast cancer cells, in contrast to benign tumors where LDHB was predominantly localized in breast epithelium." (PMID 33353120, 2020). "The function of LDHB in breast cancer or more specifically TNBC remains ambiguous." (PMID 33324565, 2020). "MATN2 and SCGB2A2 are upregulated in ovarian cancer; S100P is upregulated in prostate cancer, invasive ductal carcinomas, and pancreatic cancer; LDHB is a biomarker for triple negative breast cancer; and TNC is associated with Tamoxifen resistance in breast cancer." (PMID 27449296, 2016). "In breast cancer, LDHB down-regulation induced by the tumor-derived miR-375 in the TAMs will drive macrophage polarization and subsequent tumor growth, whereas the decreased activity of LDHB in the carcinoma cell may inhibit tumor growth." (PMID 36612084, 2022). "For example, LDHB is critical for sustaining tumor cell proliferation in TNBC and BLBC, where its activity significantly exceeds that observed in other breast cancer subtypes." (PMID 40733189, 2025). "Luminal A breast cancer often exhibits high levels of monocarboxylate transporter (MCT) 1, LDHB, and glutamine synthetase, resulting in reduced lactate secretion and enhanced glutamine synthesis." (PMID 40630197, 2025). "In breast cancer, the HMGB2 is regulated with ER, LDHB, and FBP1 to promote the endocrine therapy resistance and tumorigenesis of tumor cells." (PMID 35962344, 2022). "Knockdown of LDHA or LDHB knockdown is reported to reduce the LDH activity and lactate production in breast carcinoma cells." (PMID 36612084, 2022). "Mechanically, promotion of breast cancer progression by HMGB2 directly and significantly correlated with activation of LDHB expression and inactivation of FBP1 expression." (PMID 29463261, 2018). "Notably, during the developmental trajectory of cells, breast cancer stem cells (BCSCs) tend to express genes such as IER3 and GADD45B at the early stage, while genes like NNMT and LDHB are preferentially expressed in the BCSCs-2 developmental state." (PMID 40092692, 2025). "We discovered a non-redundant role of LDHB in macrophages and explored its pathophysiological relevance in breast cancer." (PMID 34158867, 2021). "Unlike LDHA, LDHB is negligibly expressed in luminal breast cancer cells like MCF-7 and its knockdown had no major effect on cell proliferation." (PMID 34158867, 2021).
breast carcinoma (continued). "Overall, sensitivity of cells to LDH inhibition as measured by lactate flux varied greatly between cell lines and did not correlate with levels of either LDHA or LDHB expression, except in breast cancer." (PMID 24280423, 2013). "In light of the cell-specific protein localization of LDHB in adipocytes and LDHA in cancer cells, which was particularly prominent at the invasive front of the tumor, it is worth considering lactate oxidation by adipose tissue as part of the metabolic coupling in premenopausal breast cancer." (PMID 33353120, 2020). "MCF-7/ADR cells also have markedly increased expression of the L-lactate dehydrogenase B chain (LDHB) relative to MCF-7 cells, which support the hypothesis that LDHB is a predictive marker for the response for patients with breast cancer receiving neoadjuvant chemotherapy." (PMID 25818003, 2015). "Notably, the genes LDHB, MMP7, KRT5, KRT14 and KRT15, which were significantly upregulated in the PIPET_Basal subpopulation, are recognized as specific biomarkers of the basal-like molecular subtype or genes typically highly expressed in basal-like breast cancer." (PMID 38819254, 2024). "Furthermore, the expression of this gene was also significantly increased by RIP140 silencing in the breast cancer cell lines MCF7 and MDA-MB-436, whereas the LDHB and GLUT4 levels did not change (data not shown)." (PMID 35501580, 2022).
colorectal cancer (23 papers, 2016 to 2025). A primary or metastatic malignant neoplasm that affects the colon or rectum. "For instance, SIRT5 expression promotes colorectal cancer cell survival by stimulating autophagy through the deacetylation of lactate dehydrogenase B, which facilitates lysosomal acidification." (PMID 41304967, 2025). "In particular, we knocked down LDHA and LDHB to lower histone lactylation levels, and then we restored GDF15 in LDH-deficient colorectal cancer cells." (PMID 40775002, 2025). "SIRT5 deacetylates lactate dehydrogenase B (LDHB) and promotes its enzymatic activity, thus generating additional protons and increasing autophagy and tumorigenesis in colorectal cancer, and the knockdown of SIRT5 reduces cancer cell proliferation." (PMID 36010594, 2022). "SIRT5 was also found to modulate the deacetylation of LDHB and induce the autophagy in colorectal cancer." (PMID 35136826, 2022). "SIRT5, which is demonstrated to directly deacetylate LDHB at lysine 329, increases LDHB activity and promotes autophagy in human colorectal cancer, leading to tumor growth and poor prognosis." (PMID 36407005, 2022). "Such differential patterns of LDHA and LDHB expression were observed in highly proliferated cells, such as colorectal cancer cells and lung cancer cells." (PMID 36190974, 2022). "In colorectal cancer, Krüppel-like transcription factor 14 (KLF14) targets LDHB to inhibit glycolysis and is associated with higher overall survival and disease-free survival." (PMID 36612084, 2022). "Spheroid co-culture experiments using colorectal carcinoma HCT116 spheroids revealed that LDHB-overexpressing cells preferentially migrated into spheroids and showed higher expression of cytotoxic effector molecules within the spheroids." (PMID 35682650, 2022). "miR-335-5p functions via lactate dehydrogenase B to exert tumor inhibitory effects in colorectal cancer." (PMID 33482821, 2021). "As an important glycolytic enzyme, LDHB has been reported to be overexpressed in triple-negative breast cancer and promote the tumorigenesis of colorectal cancer." (PMID 32484203, 2020). "Additionally, SIRT5 acts as a deacetylase, desuccinylase, and a demalonylase to activate target proteins such as lactate dehydrogenase B, and transketolase, promoting cell proliferation, oxidative stress, and cell survival in colorectal cancer." (PMID 41304967, 2025). "For example, sirtuin 5 (SIRT5) can deacetylate LDHB at lysine 329 to accelerate the growth of colorectal cancer, and the increased phosphorylation of LDHB at serine 162 can promote NAD+ regeneration, glycolytic flux, lactate production, and glycolytic intermediate generation." (PMID 36612084, 2022). "In addition, miR-335-5p weakens colorectal cancer cell proliferation and migration via reducing LDHB." (PMID 34362407, 2021). "It was discovered that LDH-B expression was increased in cetuximab-resistant colorectal cancer cell lines, which suggests that LDHB might play a significant role in cancers’ acquisition of drug resistance." (PMID 32528540, 2020). "Deacetylated LDHB increased autophagy and accelerated the growth of colorectal cancer (CRC) cells." (PMID 30443978, 2019). "Moreover, recently reported findings revealed that the transcription factor KLF14 participates in antineoplastic effects during the development of colorectal cancer (CRC) by regulating the glycolytic enzyme LDHB, which confirmed the regulatory effect of KLF14 on glycolysis." (PMID 34983946, 2022). "In colorectal cancer, metabolic enzymes such as SHMT2, LDHB, and TFEB are selectively targeted through acetylation-dependent degradation or stabilization, reflecting the metabolic vulnerability of this tumor type." (PMID 41213956, 2025). "To investigate the potential role of histone lactylation in the development of colorectal cancer, we reduced endogenous LDHA and LDHB to lower global lactylation and H3K18 lactylation levels." (PMID 40775002, 2025).